RNU1-153P (RNA, U1 small nuclear 153, pseudogene)
Gene: Small nuclear RNA gene on chromosome 1 (145,169,519 to 145,169,664, forward strand). Ensembl gene ENSG00000277678.
Homologues: Orthologues: chimpanzee U1 (100% identical), macaque U1 (91% identical), dog U1 (71% identical), guinea pig U1 (64% identical). Paralogues in human: RNU1-143P (100% identical), RNU1-68P (100% identical), U1 (100% identical), RNU1-5P (94% identical), U1 (92% identical), RNU1-6P (90% identical), RNU1-1 (75% identical), RNU1-19P (75% identical), RNU1-2 (75% identical), RNU1-27P (75% identical), RNU1-28P (75% identical), RNU1-3 (75% identical), and 134 more.